ABL1 (ABL proto-oncogene 1, non-receptor tyrosine kinase)
Diseases named in the same sentence as ABL1 in open-access papers (continued):
Sharing a sentence is not in itself a finding about the gene and the disease.
leukemia (continued). "Although leukemia progression was not achieved by simple transplantation of human CD34 + cord blood cells retrovirally transduced with p210 BCR::ABL1 cDNA into NOD-SCID mice, simultaneous transduction of BMI1 cDNA induced ALL progression." (PMID 35999358, 2023). "The translocation generating BCR::ABL1 that drives Ph+ tumors such as SUP-B15 is described as able to induce leukemia onset and development by itself, and Ph+ tumors tend to express simple karyotypes, being overly dependent on BCR::ABL1 expression, a condition denominated “oncogene addiction”." (PMID 38067214, 2023). "FDA-approved drugs that inhibit ABL1/2 and DDR1 have been used for decades to treat leukemia." (PMID 36765910, 2023). "More precisely, targeting a single mutation (as tyrosine kinase inhibitors for BCR::ABL1 fusion gene, FLT3 or IDH1/2 mutations) is not the “magic bullet” since leukemia heterogeneity will allow tumor escape via clonal drift under chemotherapy pressure." (PMID 37444390, 2023). "Thus, we induced DSBs at specific breakpoints of BCR and ABL1 genes, using the CRISPR/Cas9 system in a human factor-dependent leukemia cell line." (PMID 35999358, 2023). "The absence of ABL1 facilitated proliferation and genomic instability while abrogating differentiation of these leukemia cells resulting in highly malignant leukemia phenotypes." (PMID 36959186, 2023). "Given our findings here that normal ABL1 activity is important for MLH1 protein stability in at least a portion of cellular MLH1, it raises interesting questions as to what MLH1 dynamics are in leukemia cells harboring BCR-ABL." (PMID 36338985, 2022). "The BCR::ABL1 fusion oncoprotein, which has tyrosine kinase activity and activates different downstream signal pathways, such as JAK-STAT, MAPK/ERK, and PI3K/Akt/mTOR, promotes the occurrence and development of leukemia." (PMID 36263131, 2022). "ddPCR simultaneously quantitated mRNA expression of WT1, PRAME, BIRC5, and ABL1 and the TAA/ABL1 blood ratio was measured in patients with and without active leukemia after HCT." (PMID 36248870, 2022). "In summary, we have developed a new method for blood MRD monitoring of leukemia after HCT and present preliminary data that the TAA/ABL1 ratio may may serve as a novel surrogate biomarker for relapse of acute leukemia after HCT." (PMID 36248870, 2022). "The IL2RA mRNA and its protein CD25 levels were assayed in 54 primary AML BM samples by TaqMan RQ-PCR and FCM respectively, in which the mRNA level was shown as 2−∆Ct of IL2RA gene relative to ABL1 gene and the expression level of CD25 protein was illustrated as percentage in leukemia blast cells." (PMID 31171000, 2019). "Some therapeutically-targetable leukemia antigens originate from oncogenesis itself and are leukemia cell-specific, such as the BCR/ABL1 fusion protein in CML and Philadelphia (Ph)+ ALL, PML/RAR-α in acute promyelocytic leukemia, FLT3-ITD and mutated NPM1 in AML and IDH1/2." (PMID 29466292, 2018). "Loss of ABL1 autoregulation contributes to the constitutive activation of BCR::ABL1, driven by homo-oligomerisation of BCR::ABL1 mediated by the coiled-coil domain of the breakpoint cluster region (BCR) protein, which in turn induces uncontrolled proliferation and survival of leukemia stem cells." (PMID 38965368, 2024). "One possible explanation for this discrepancy between transgenic models and knock-in models is that promoter activity of the bcr gene in the knock-in mice might not be sufficiently high for leukemia transformation by p210 BCR::ABL1." (PMID 35999358, 2023). "Notably, B-cell leukemia was developed in knock-in mice of p190 BCR::ABL1 cDNA, while leukemia progression was not confirmed in those of p210 BCR::ABL1." (PMID 35999358, 2023). "Finally, within CSF + LM group, differential protein profiles were observed between leukemia and lymphoma (such as FCGR1, CR2, ABL1, PTPRC, SELP, ITGB1, COL9A3 or ITGAX), which could subtype the CSF + LM depending on the primary tumor." (PMID 35053611, 2022).
leukemia (continued). "Moreover, in the mice p210 BCR::ABL1‐transduced ALL model, in vivo conditional knockout of the integrin α6 gene sensitized the leukemia cells to nilotinib treatment, suggesting that the laminin/CD49f interaction might also be involved in the TKI‐resistance of Ph‐positive ALL." (PMID 38577721, 2024). "To test our RoCK and ROI targeted enrichment strategy, we used a mix of three patient-derived leukemia cell lines containing either a minor fusion (SUP-B15, e1a2), major fusion (K562, e14a2) or no BCR::ABL1 fusion (Loucy)." (PMID 41372142, 2025). "NUP98-PMX1;Abl1−/− murine leukemia cells were highly sensitive to buparlisib when compared to NUP98-PMX1;Abl1 + /+ counterparts, at the same time ABL1 did not affect the sensitivity of AML1-ETO cells to the inhibitor." (PMID 36959186, 2023). "ABL1/2 (a.k.a. c-ABL, ARG) non-receptor tyrosine kinases are most known for their oncogenic roles in leukemia; however, accumulating evidence over the past two decades indicates that they also play critical roles in solid tumors including melanoma." (PMID 36765910, 2023). "Of the 19 patients with active disease, including those leukemias without elevated TAA/ABL1, the blood levels of WT1/ABL1, PRAME/ABL1, and BIRC5/ABL1 exceeded healthy donors (p<0.0001, p=0.0286, and p=0.0064 respectively)." (PMID 36248870, 2022).
acute lymphoblastic leukemia (271 papers, 2006 to 2026). Leukemia with an acute onset, characterized by the presence of lymphoblasts in the bone marrow and the peripheral blood. "Here, we report the case of a ponatinib-resistant Philadelphia chromosome-positive acute lymphoblastic leukemia (Ph + ALL) patient harboring a BCR::ABL1 p.I293_K294insSLLRD mutation." (PMID 39774950, 2025). "Mutations of ABL1 are the dominant mechanism of relapse in Philadelphia chromosome-positive acute lymphoblastic leukemia (Ph + ALL)." (PMID 32457305, 2020). "However, ABL1 KD mutations are relatively unstudied in BCR::ABL1‐positive acute lymphoblastic leukemia (ALL)." (PMID 39440695, 2024). "The pathogenic role of the overactivated ABL1 tyrosine kinase (TK) pathway is well recognized in some forms of BCR-ABL1 like acute lymphoblastic leukemia (ALL); TK inhibitors represent a useful therapeutic choice in these patients who respond poorly to conventional chemotherapy." (PMID 34867354, 2021). "Emergence of ABL1 kinase inhibitor resistant clones may cause disease relapse in Philadelphia chromosome-positive acute lymphoblastic leukemia." (PMID 32581241, 2020). "PEER and BE-13 cells are characterized by the NUP214-ABL1 fusion gene mutation, that is the most frequent and highly specific ABL1 fusion protein for T-lineage acute lymphoblastic leukemia, that transforms T-cells and is a constitutively active tyrosine kinase with oncogenic potential." (PMID 25788264, 2015). "BCR::ABL1 oncogene is also present in 20–30% of acute lymphoblastic leukemia (Ph + ALL) cases, a rare aggressive lymphoid malignancy that predominantly involves B-lymphocytes." (PMID 39774950, 2025). "Philadelphia chromosome-positive acute lymphoblastic leukemia (Ph+ ALL) is a distinct subtype of ALL characterized by the presence of the BCR::ABL1 fusion gene, which encodes a constitutively active BCR-ABL1 tyrosine kinase oncoprotein." (PMID 41170452, 2025). "An interesting study of deep molecular profiling revealed three transcriptomic subtypes of BCR::ABL1 lymphoblastic leukemia, each representing a maturation arrest at a stage of B-cell progenitor differentiation." (PMID 40076750, 2025). "Acute lymphoblastic leukemia harboring the ETV6::ABL1 fusion constitutes a rare but clinically relevant subtype, typically associated with poor prognosis." (PMID 41228238, 2025). "Several studies have suggested that chemotherapy-free regimens consisting of blinatumomab and a BCR::ABL1 tyrosine kinase inhibitor are highly effective in Philadelphia chromosome-positive acute lymphoblastic leukemia (Ph + ALL)." (PMID 40369607, 2025). "We next applied our targeting and data analysis strategy to a BCR::ABL1-positive B-cell precursor acute lymphoblastic leukemia (BCP-ALL) patient sample at first diagnosis." (PMID 41372142, 2025). "To date, ETV6::ABL1 has been reported on various hematological malignancies, including B/T-acute lymphoblastic leukemia, acute myeloid leukemia (AML), and myeloproliferative neoplasm (MPN)." (PMID 39066837, 2024). "Philadelphia-positive acute lymphoblastic leukaemia (ALL) is also defined by the BCR::ABL1 fusion gene, however, the majority of fusion genes in ALL arise from rearrangements within the minor breakpoint cluster region (m-bcr)." (PMID 37496024, 2023). "Of those 39 individuals with BCR::ABL1 gene fusion, 37 (95%) presented with acute lymphoid leukemia." (PMID 37686670, 2023). "The BCR::ABL1 gene most commonly leads to a blood cancer called chronic myeloid leukaemia (CML), but can also cause an acute leukaemia, more commonly acute lymphoblastic leukaemia and rarely, acute myeloid leukaemia." (PMID 38550948, 2023). "For example, dasatinib is used in the activation of EphA3 via mediating role of the ABL1 protein kinase domain in lymphoblastic leukemia, and PORCN is considered suitable for the palmitoleation of mammalian Wnts to treat ovarian cancer." (PMID 36139498, 2022).
acute lymphoblastic leukemia (continued). "IKZF1, the gene encoding Ikaros, is recurrently mutated in human B cell progenitor acute lymphoblastic leukemias (B-ALLs) with translocations between the IGH locus and the ABL1 proto-oncogene (BCR-ABL1)." (PMID 30978178, 2019). "Recent studies revealed that a substantial proportion of patients with high-risk B-cell precursor acute lymphoblastic leukemia (BCP-ALL) harbor fusions involving tyrosine kinase and cytokine receptors, such as ABL1, PDGFRB, JAK2 and CRLF2, which are targeted by tyrosine kinase inhibitors (TKIs)." (PMID 27176795, 2016). "Furthermore, through this approach, BCR::ABL1 kinase activity was barely detectable in CP-CML compared to Ph+ acute lymphoblastic leukemia primary samples, where kinase activity is comparable to those measured in Ph+ cell lines." (PMID 35756686, 2022). "This real-life study compared mutation profiles and their impact on outcomes in 80 AYA, 97 adult, and 16 pediatric CML-CP patients, alongside 81 BCR::ABL1-positive acute lymphoblastic leukemia (Ph+ ALL) patients." (PMID 40295826, 2025). "The application of tyrosine kinase inhibitors and targeted immunotherapy has revolutionized the therapeutic strategies and clinical outcome for BCR::ABL1-positive B-cell acute lymphoblastic leukemia (BCR::ABL1+ B-ALL)." (PMID 39231779, 2024). "NUP214::ABL1 fusion is detected in 6% of T-cell acute lymphoblastic leukemia (T-ALL), and is very rare in B-ALL." (PMID 36172171, 2022). "The historical standard of care for adults with newly diagnosed Philadelphia chromosome-positive (Ph+) acute lymphoblastic leukemia (ALL) was chemotherapy plus a BCR::ABL1 tyrosine kinase inhibitor (TKI), followed by allogeneic stem cell transplant (alloSCT) in first remission." (PMID 40369607, 2025). "Acute lymphoblastic leukemia (ALL) is the most common childhood cancer and the presence of BCR::ABL1 fusion in p190 isoform is a marker for worse prognosis, associated with treatment resistance and reduced overall survival." (PMID 38067214, 2023). "The screening of the BCR::ABL1 kinase domain (KD) mutation has become a routine analysis in case of warning/failure for chronic myeloid leukemia (CML) and B-cell precursor acute lymphoblastic leukemia (ALL) Philadelphia (Ph)-positive patients." (PMID 35906470, 2022). "Asciminib (formerly ABL001), a potent and selective allosteric ABL1 inhibitor, is undergoing clinical development testing in patients with CML and Philadelphia chromosome-positive (Ph+) acute lymphoblastic leukemia (ALL)." (PMID 34055612, 2021). "ABL001 is a potent and selective ABL1 inhibitor that is undergoing clinical development testing in patients with CML and Ph + acute lymphoblastic leukemia." (PMID 29456860, 2018). "Upregulation of ABL1 gene expression is a common feature of BCR–ABL1-positive versus -negative acute lymphoblastic leukemia." (PMID 31745703, 2020). "The oncogene BCR::ABL1 is a key player in chronic myeloid leukemia (CML), as well as in acute lymphoblastic leukemia (ALL), collectively known as Philadelphia chromosome-positive (Ph+) neoplasms." (PMID 38906962, 2024). "Philadelphia chromosome-positive B cell acute lymphoblastic leukemia (B-ALL), characterized by the BCR::ABL1 fusion gene, remains a poor prognosis cancer needing new therapeutic approaches." (PMID 38457494, 2024). "Z‐fusion genes are the most frequent fusion genes in Japanese adult BCR::ABL1‐negative B‐cell acute lymphoblastic leukemia (B‐ALL), while they are much less frequent in the US." (PMID 39015025, 2024). "BCR/ABL1 plays a key role in development of chronic myelogenous leukemia (CML) and in some cases of Philadelphia chromosome-positive acute lymphoblastic leukemia (Ph1-ALL)." (PMID 37165001, 2023).
acute lymphoblastic leukemia (continued). "Philadelphia chromosome-positive (Ph-positive) acute lymphoblastic leukemia (ALL) is the most common subtype of ALL in adults, characterized by the abnormal formation of the Philadelphia chromosome, which leads to the development of the BCR::ABL1 gene with increased activity." (PMID 37798335, 2023). "Furthermore, S1P inhibits classical apoptosis in T acute lymphoblastic leukemia (T-ALL) and SPHK1 level is increased in B-ALL, contributing to the development of murine BCR/ABL1 ALL." (PMID 29216917, 2017). "The Ph translocation leads to the constitutive activation of the ABL1 tyrosine kinase, which plays a central role in the pathogenesis of several hematologic malignancies, including CML, B-cell acute lymphoblastic leukemia (B-ALL), mixed-phenotype acute leukemia and, in rare cases, AML." (PMID 41009384, 2025). "The inclusion of BCR::ABL1 tyrosine-kinase inhibitor (TKI) in the first-line treatment of chronic myeloid leukemia (CML) and positive B-cell precursor acute lymphoblastic leukemia (ALL) with Philadelphia (Ph) chromosome increased the life expectancy of these patients." (PMID 35906470, 2022). "Constitutive ABL1 activity plays a crucial role in Philadelphia chromosome (Ph)-positive chronic myeloid leukemia (CML) and acute lymphoblastic leukemia (ALL) and AML as well as in Ph-negative MPN, Ph-like ALL and acute Tcell ALL (T-ALL)." (PMID 35941390, 2022).
myeloproliferative neoplasm (194 papers, 2009 to 2026). A clonal hematopoietic stem cell disorder, characterized by proliferation in the bone marrow of one or more of the myeloid (i.e., granulocytic, erythroid, megakaryocytic, and mast cell) lineages. "Chronic myeloid leukemia (CML) is a triphasic myeloproliferative neoplasm characterized by the breakpoint cluster region-Abelson BCR::ABL1 fusion gene, typically detected by reverse transcription-quantitative polymerase chain reaction (RT-qPCR)." (PMID 41869197, 2026). "This genetic alteration leads to the production of an oncoprotein BCR::ABL1 with constitutively active ABL1 tyrosine kinase activity, whose deregulated action is responsible for the development of this myeloproliferative neoplasm." (PMID 37444494, 2023). "Chronic myeloid leukemia (CML) is a myeloproliferative neoplasm initiated by the presence of the fusion gene BCR::ABL1." (PMID 36293127, 2022). "Calreticulin (CALR) mutations are prevalent in 20%-30% of patients with BCR::ABL1-negative myeloproliferative neoplasms (MPN)." (PMID 41532194, 2026). "Constitutive JAK/STAT pathway activation is crucial in the pathogenesis of BCR::ABL1-negative myeloproliferative neoplasms (MPN), but has not yet been linked to interferon (IFN)-γ signaling and tumor microenvironment." (PMID 40764668, 2025). "Minor revisions have been made to the diagnostic criteria for BCR::ABL1-negative myeloproliferative neoplasms." (PMID 39682300, 2024). "Chronic myeloid leukemia (CML), a rare myeloproliferative disease, is associated with chromosomal translocation (i.e., Philadelphia chromosome), which encodes BCR::ABL1 oncoprotein, through the fusion of BCR and ABL1 genes, with active tyrosine kinase activity." (PMID 37358999, 2023). "CALR mutations are known drivers of myeloproliferative neoplasms and may therefore contribute to a clonal advantage and expansion even after the BCR::ABL1 clone has been eradicated." (PMID 35902731, 2022). "The JAK2V617F variant constitutes a genetic alteration of higher frequency in BCR/ABL1 negative chronic myeloproliferative neoplasms, which is caused by a substitution of a G ˃ T at position 1849 and results in the substitution of valine with phenylalanine at codon 617 of the polypeptide chain." (PMID 35204792, 2022). "The clonal composition of myeloproliferative neoplasms (MPN) harboring both JAK2 V617 F and BCR::ABL1 and the outcomes of these patients are unclear and management remains challenging." (PMID 40299271, 2025). "In this review, we summarize molecular drug resistance biomarkers in targeted therapies in BCR::ABL1-driven chronic myeloid leukemia (CML) and JAK2-driven myeloproliferative neoplasms (MPNs)." (PMID 39104388, 2024). "Essential thrombocythemia and primary myelofibrosis belong to the group of BCR::ABL1-negative myeloproliferative neoplasms." (PMID 39960584, 2026). "Over the past decades, significant progress has been made in our understanding of the pathophysiology of BCR::ABL1-negative myeloproliferative neoplasms." (PMID 39960584, 2026). "The classical BCR::ABL1 negative myeloproliferative neoplasms are a group of blood disorders characterized by the overproduction of mature blood cells in the bone marrow." (PMID 39960584, 2026). "BCR::ABL1-negative myeloproliferative neoplasms are chronic diseases characterized by high symptom burden due to systemic inflammation." (PMID 41559233, 2026). "More than a decade after its discovery, advances have been made in understanding the oncogenic role of mutant CALR in BCR::ABL1-negative myeloproliferative neoplasms (MPNs)." (PMID 41228192, 2025). "Myelofibrosis (MF) is a life-threatening complication of BCR:ABL1-negative myeloproliferative neoplasms (MPNs) induced by the MPN cell clonal proliferation, leading to bone marrow fibrosis, extramedullary hematopoiesis, and acute leukemia transformation." (PMID 39470742, 2024).